OAS2 (2'-5'-oligoadenylate synthetase 2)
Diseases named in the same sentence as OAS2 in open-access papers (continued):
Sharing a sentence is not in itself a finding about the gene and the disease.
prostate carcinoma (2 papers, 2012 to 2016). A carcinoma that arises from epithelial cells of the prostate gland. "Two sub-pathways (intracellular antiviral molecules and extracellular pattern recognition) and four genes in these sub-pathways (TLR1, TLR6, OAS1, and OAS2) were nominally associated with advanced prostate cancer risk and harbor several SNPs nominally associated with advanced prostate cancer risk." (PMID 23272139, 2012). "Expression of several TLRs and OAS2 in PBMCs was also suggested to play a role in advanced prostate cancer via mechanisms of inflammation and innate immunity." (PMID 26979060, 2016). "Within those sub-pathways, 5 genes (TLR1, TLR6, OAS1, OAS2, and COX-2) were nominally associated with advanced prostate cancer risk." (PMID 23272139, 2012).
Stroke (2 papers, 2023 to 2025). Sudden impairment of blood flow to a part of the brain due to occlusion or rupture of an artery to the brain. "In conclusion, our study suggests that aging stroke may be regulated by IFI27 and OAS2 via the type I interferon signaling pathway." (PMID 36862915, 2023).
testicular cancer (2 papers, 2023 to 2025). A primary or metastatic malignant neoplasm that affects the testis. "A recent report suggested that piR-36249 regulates testicular cancer progression by engaging with DHX36 to regulate OAS2." (PMID 37662498, 2023).
tuberculosis (2 papers, 2022 to 2024). A chronic, recurrent infection caused by the bacterium Mycobacterium tuberculosis. "The 2′,5′-oligoadenylate synthetase (OAS) family, including OAS1, OAS2, and OAS3, is composed of IFN-induced antiviral enzymes and has been well studied in the field of tuberculosis." (PMID 36567857, 2022).
acute myeloid leukemia (1 paper, 2023). Acute myeloid leukemia (AML) is a group of neoplasms arising from precursor cells committed to the myeloid cell-line differentiation. "In acute myeloid leukemia (AML), OAS2 expression was shown to induce chemoresistance." (PMID 36900319, 2023).
Arthritis (1 paper, 2020). Inflammation of a joint. "Active SLE patients with arthritis showed higher OAS2 and OAS3 expression in PBMCs and CD19+ B cells and OAS2 expression in CD4+ T cells (P<0.05)." (PMID 32321151, 2020). "Moreover, active SLE patients with renal disorders and arthritis showed higher OAS2, OAS3, and OASL expression than patients without these symptoms." (PMID 32321151, 2020).
bladder urothelial carcinoma (1 paper, 2022). "The genes co-expressed with OAS1, OAS2, OAS3, and OASL in Sanchez-Carbayo Bladder 2 dataset were identified using Oncomine in 48 normal samples, 81 filtrating bladder urothelial carcinoma tissues, and 28 superficial bladder cancer tissues." (PMID 36162993, 2022).
Bovine mastitis (1 paper, 2022). INFLAMMATION of the UDDER in cows. "Our data suggest that genes TLR4, NOD2, CXCL8, and OAS2 are key components involved in the host immune response to bovine mastitis and that the lncRNAs MSTRG25101.2, MSTRG.56327.1, and MSTRG.18968.1 adjacent to the SCC QTL and SCS QTL may potentially regulate expression of these candidate genes." (PMID 36204322, 2022).
chronic fatigue syndrome (1 paper, 2013). "An association between fatigue and overexpression of 2′-5′-oligoadenylate synthetase 2 (OAS2), a gene linked to chronic fatigue syndrome, was noted in cancer patients receiving chronic IFNα therapy." (PMID 23959120, 2013).
Cirrhosis (1 paper, 2012). A chronic disorder of the liver in which liver tissue becomes scarred and is partially replaced by regenerative nodules and fibrotic tissue resulting in loss of liver function. "ATG16L2, DEFB114, FAM14B, IFNA21, IL8RB and KIR2DL genes were up-regulated in cirrhosis, whereas, FCRL3, IFITM2 and OAS2 genes were up-regulated in initial fibrosis." (PMID 22397681, 2012).
co-infection (1 paper, 2020). "The co-infection allowed observation of multiple genes involved in the obstruction of the viral life cycle within the host such as MX1,MX2, OASL, OAS2, heat shock protein family A (Hsp70) member 8 (HSPA8), and radical S-adenosyl methionine domain containing 2 (RSAD2)." (PMID 33187194, 2020).
colon cancer (1 paper, 2023). "In a study of primary colon cancer, genes such as IGBP3, OAS2, MX1, and Robo2 were found as prognostic markers in an independent series of colon cancer patients." (PMID 36759842, 2023).
dermatomyositis (1 paper, 2021). Dermatomyositis (DM) is a type of idiopathic inflammatory myopathy characterized by evocative skin lesions and symmetrical proximal muscle weakness. "In conclusion, a total of 3 genes associated with the development of dermatomyositis—MX2, OAS1, and OAS2—were identified in this study through a series of information biology analyses, which are expected to be biomarkers or drug targets to some extent for the diagnosis of dermatomyositis." (PMID 35003257, 2021). "The results showed that MX2, OAS1, and OAS2 were significantly upregulated in the GSE11971 and GSE142807 datasets compared to normal samples in dermatomyositis samples." (PMID 35003257, 2021).
endometrial cancer (1 paper, 2017). Primary or metastatic malignant neoplasm involving the endometrium (mucous membrane that lines the endometrial cavity). "In the endometrial cancer patients, expression of OAS2 was upregulated at 48 h in patient E9, who was recorded as having the second highest late toxicity score of grade 3." (PMID 28443095, 2017). "In endometrial cancer patients, we observed by simple visual screening that the expression of CD40 and OAS2 was particularly variable in patient E9 at the different time points studied although the number of patients studied here didn’t allow us to conclude in terms of statistical significance." (PMID 28443095, 2017).
enterovirus infection (1 paper, 2025). "This aligns with clinical findings that children who harbor OAS2 polymorphisms have increased susceptibility to enterovirus infection." (PMID 40806174, 2025).
Granuloma (1 paper, 2014). A compact, organized collection of mature mononuclear phagocytes, which may be but is not necessarily accompanied by accessory features such as necrosis. "The expression of IFIT1 genes and OAS2 genes was similar in C. burnetii-induced granulomas from patients with Q fever and healthy controls." (PMID 25566510, 2014). "We investigated the expression of IFIT1 and OAS2, two genes belonging to type 1 IFN pathway which were specifically modulated in C. burnetii-induced granulomas." (PMID 25566510, 2014). "The stimulation of type 1 IFN pathway (OAS2 and IFIT1 genes) was similar in granulomas from healthy controls or patients with Q fever." (PMID 25566510, 2014).
head and neck cancer (1 paper, 2017). A primary or metastatic malignant neoplasm affecting the head and neck. "The expression of OAS2 was also upregulated in the head and neck cancer patient N5, which reported the highest level of toxicity, grade 3." (PMID 28443095, 2017). "Of importance, the pattern of expression was different from patient E9, the nCounter analysis also identified OAS2 as well as another gene CXCR1, showing an increased expression in the head and neck cancer patient N5 at 5 weeks." (PMID 28443095, 2017).
heart failure (1 paper, 2024). Inability of the heart to pump blood at an adequate rate to meet tissue metabolic requirements. "This current study reveals that OAS2 is significantly expressed in the myocardium of heart failure patients, presenting a fresh insight into the mechanism underlying HF." (PMID 38355637, 2024). "However, limited attention has been given to the investigation of OAS2 in the context of heart failure." (PMID 38355637, 2024).
Hepatic steatosis (1 paper, 2023). Steatosis is a term used to denote lipid accumulation within hepatocytes. "It has been confirmed that the expression of OAS2 is increased in the colonic mucosa of patients with active UC and plays an important role in hepatic steatosis and HCV infection." (PMID 37898694, 2023).
infiltrating bladder urothelial carcinoma (1 paper, 2022). An invasive transitional cell carcinoma that arises from the urinary bladder urothelium. "OAS2 was 2.470 times higher in infiltrating bladder urothelial carcinoma in the Sanchez-Carbayo bladder 2 dataset, and was 1.435 times higher than with the respective normal tissues in superficial bladder cancer from the Lee Bladder dataset." (PMID 36162993, 2022).
ischemic stroke (1 paper, 2025). A stroke disorder caused by obstruction of blood flow to the brain, due to thrombotic (local blood clot formation) or embolic (due to a blood clot or other material traveling from another site) event. "Considering that the immune response is a pivotal mechanism in ischemic stroke, it can be inferred that OAS2 has a significant impact on the progression of this condition." (PMID 40371070, 2025). "Comprehensive bioinformatics analysis identified three hub genes—OAS2, TMEM106A, and ABCB1—with high prognostic value for ischemic stroke." (PMID 40371070, 2025). "Furthermore, we established a gene panel that includes OAS2, TMEM106A, and ABCB1 to evaluate their potential in predicting the diagnosis of atherosclerotic plaques and ischemic stroke." (PMID 40371070, 2025). "Furthermore, our results indicate that OAS2, TMEM106A, and ABCB1 may serve as promising candidates for the diagnosis and assessment of atherosclerotic plaques and ischemic stroke." (PMID 40371070, 2025).
lung carcinoma (1 paper, 2017). "Our microarray data analysis revealed and RT-qPCR confirmed the increased mRNA expression of all of the OAS gene family members (OAS1, OAS2, OAS3, OASL) and XAF1 and IRF7 in the lung cancer cell line A549 after transfection with BNC2." (PMID 28184177, 2017).
lung disease (1 paper, 2021). "By specific lung cell isolation, several interferon-related and autoimmune genes were disproportionately expressed among CIA and CIA+ODE (e.g. Oasl1, Oas2, Ifit3, Gbp2, Ifi44, and Zbp1), corresponding to RA and RA-associated lung disease." (PMID 33577605, 2021).
lymphopenia (1 paper, 2022). Reduction in the number of lymphocytes. "For examples, monocyte alterations (CD74, CIITA mRNA), lymphopenia (CD3, IL7R mRNA), increased anti-inflammatory response (IL10, IL1RN mRNA), altered IFN response (OAS2, IFNG mRNA) were observed." (PMID 36389738, 2022).
malaria (1 paper, 2018). Malaria is a serious and sometimes fatal disease caused by a parasite that commonly infects a certain type of mosquito which feeds on humans. "The immunity related genes that are down-regulated in the malaria severity signature are: PRF1, GNLY, OAS2, MX1, OAS3 and CCL5." (PMID 29642892, 2018).
neuroblastoma (1 paper, 2023). Neuroblastoma (NB) is the most common solid, extracranial childhood tumor. "Here, we describe the protein expression levels of OAS1, OAS2, OAS3, and OASL in cells forming the NVU, such as primary human brain pericytes, astrocytes, EC, immortalized human microglial cells, and SH-SY5Y neuroblastoma cell line." (PMID 37209263, 2023). "Our studies also revealed a prominent expression of OAS2, OAS3, and OASL in SH-SY5Y cells; however, this is an immortalized neuroblastoma cell line, which does not fully represent mature neurons." (PMID 37209263, 2023).
Obesity (1 paper, 2022). Accumulation of substantial excess body fat. "A novel finding of the current study is the upregulation of OAS2 and OAS3, genes that encode oligoadenylate synthetases that synthesize 2′-5′-linked oligoadenylates, in individuals living with obesity." (PMID 35247847, 2022).
oral squamous cell carcinoma (1 paper, 2021). "2′-5′-Oligoadenylate synthetase 2 (OAS2) had increased expression and was screened to construct prognostic signature in oral squamous cell carcinoma (OSCC); meanwhile, the high expression of OAS2 was associated with poor OS." (PMID 35087823, 2021).
pancreatic adenocarcinoma (1 paper, 2022). "In Iacobuzio-Donahue Pancreas 2 dataset, OAS2 was highly expressed in pancreatic adenocarcinoma with a fold change of 3.563 compared with normal pancreatic tissues." (PMID 35719943, 2022).
pancreatic carcinoma (1 paper, 2022). "In Pei Pancreas and Segara Pancreas datasets, OAS2 was 2.129 and 1.995 times higher in pancreatic carcinoma tissues compared with respective normal pancreatic tissues." (PMID 35719943, 2022). "Results derived from these three databases all indicated that elevated levels of OAS1, OAS2, OAS3, and OASL were associated with poor overall survival (OS) in pancreatic cancer." (PMID 35719943, 2022). "OAS2 stains showed medial intensity in normal pancreatic tissues but showed strong intensity in pancreatic cancer tissues." (PMID 35719943, 2022). "The co-expressed genes that related to OAS1, OAS2, OAS3, and OASL were respectively identified in Pei Pancreas dataset of Oncomine database with 16 normal pancreatic tissues and 36 pancreatic carcinoma tissues." (PMID 35719943, 2022). "Western blotting results showed that the protein expression levels of OAS1, OAS2, OAS3, and OASL were significantly elevated in pancreatic cancer cells compared with normal pancreatic cells." (PMID 35719943, 2022). "The potential prognosis values of OAS1, OAS2, OAS3, and OASL in pancreatic cancer were investigated using Kaplan-Meier Plotter, GEPIA, and OncoLnc databases." (PMID 35719943, 2022). "Immunohistochemical stains of OAS1, OAS2, OAS3 and OASL proteins in human pancreatic cancer tissues and normal pancreatic tissues were searched from the HPA database." (PMID 35719943, 2022). "We further analyzed the mRNA levels of OAS1, OAS2, OAS3, and OASL in pancreatic cancer tissues and normal pancreatic tissues based on Oncomine and GEPIA databases." (PMID 35719943, 2022). "In addition, by analyzing the GEPIA database, the mRNA levels of OAS1, OAS2, OAS3, and OASL were all significantly higher in pancreatic cancer tissues than normal pancreatic tissues." (PMID 35719943, 2022). "The expressions of OAS2 and OAS3 had significant negative correlations with tumor purity in pancreatic cancer (cor = −0.219 and −0.182, respectively, P < 0.05)." (PMID 35719943, 2022).
pancreatic ductal adenocarcinoma (1 paper, 2022). An infiltrating adenocarcinoma that arises from the epithelial cells of the pancreas. "In Badea Pancreas and Grutzmann Pancreas datasets, OAS2 was overexpressed with a fold change respectively of 2.721 and 1.961 in pancreatic ductal adenocarcinoma compared with the respective normal tissues." (PMID 35719943, 2022).
rectal cancer (1 paper, 2025). A primary or metastatic malignant neoplasm that affects the rectum. "Given that multifractionated ionizing radiation induces the expression of immune response genes in vitro, we additionally explored whether the PARPs are co-expressed with selected OAS2, IFITM1, and IFIT1 genes in rectal cancer patients." (PMID 40646573, 2025).
reovirus infection (1 paper, 2017). "Not surprisingly, reovirus infection stimulated a strong increase in genes associated with an anti-viral response in both cell lines, including OAS1, OAS2, and OAS3." (PMID 29156834, 2017).
tick-borne encephalitis (1 paper, 2023). Tick-borne encephalitis is caused by an arbovirus of the Flaviviridae family (tick-borne encephalitis virus, TBEV), transmitted principally by the bite of the Ixodes ricinus tick. "rs1293762 (OAS-2; T > G) is involved in tick-borne encephalitis (TBE), Dengue virus, and HCV." (PMID 36833454, 2023).
tongue SCC (1 paper, 2016). "In tongue SCC, methylation levels at CpG2 and CpG3 were significantly correlated with mRNA levels (Spearman correlation coefficient rho = −0.738 (CpG2) and −0.769 (CpG3), P = 0.000), whereas in tonsillar SCC OAS2 hypomethylation at CpG2 and 3 was not correlated with gene overexpression." (PMID 27572959, 2016).
tonsillar cancer (1 paper, 2016). "DNA methylation levels of OAS2 in another 23 tonsillar cancer samples were also studied." (PMID 27572959, 2016).
infection (84 papers, 2010 to 2026). The state of being infected such as from the introduction of a foreign agent such as serum, vaccine, antigenic substance or organism. "The induction of viral RNA sensors (TLR3 and RIG-I), along with associated factors (IRF3, IFN-β, and OAS2), was low on the first day post-infection and reached peak expression by the third day." (PMID 41303574, 2025). "Representative ISG mRNA levels (IFIT1, OAS2) were also increased during infection with the nsp15 mutant in MRC-5 cells, but were induced to a similar extent in nasal ALI cultures." (PMID 41369222, 2026). "Similar results were observed with the virulent strain used in our study (26544/OG10), where expression levels for some key antiviral genes (DDX58, DHX58, IFIH1, MX1, and OAS2) decreased slightly as infection progressed." (PMID 40530033, 2025). "In contrast, in the case of attenuated NH/P68, the fold-changes values of MX1, OAS2 increased slightly as infection progressed." (PMID 40530033, 2025). "Later during infection, at 12 dpi, the top ten significantly upregulated genes with highest fold change included, similar to 4 dpi, Zbp1, Oas2, Gbp1, Ddx60, Oas1a and Mx1." (PMID 38536871, 2024). "We found that ASFV-WT infection strongly suppressed the mRNA levels of Isg56, Isg15, Mx1, and Oas2 induced by IFN-α." (PMID 38620034, 2024). "CVA6 infection leads to the increased expression of ISGs, including Oas2, Irf7, Ddx60, Ifit3, Ddx58, and Isg15, which exhibit immunopathogenic potential and are implicated in neural inflammation." (PMID 36851724, 2023). "On the other hand, P. BCG appears to be controlled from the beginning of the infection, secondary to the upregulation of the OAS2 gene that controls intracellular replication." (PMID 35562916, 2022). "As key ISGs, OAS1, OAS2, and OAS3 are evolutionarily conserved and are associated with the early inflammatory response during infection." (PMID 34490145, 2021). "OAS1, OAS2, OAS3, and OASL expression levels are also directly linked to mycobacterial pathogenicity during the early post-infection period, as they can restrict MTB intracellular replication in macrophages by regulating cytokine secretion." (PMID 34490145, 2021). "We also examined OAS2 expression in A549 cells infected with ZIKV at different multiplicity of infection (MOI)." (PMID 32276512, 2020). "Previous studies showed significant association between OAS2, OAS3, and OASL expression and IFNα level during infection of virus or bacteria." (PMID 32321151, 2020). "The classical ISGs were strongly induced by CDV-infection with particularly high levels for Isg15, Ifi44l, Isg56, Oas2 and Mx2 (fold change up to 928.35, 419.93, 179.05, 173.57 and 147.59)." (PMID 30939763, 2019). "The expression of the ISG oligo-adenylate synthase 2 (OAS2) was consistently induced by AdEGFPuci infection at 72 h, indicative of an antiviral state." (PMID 28107341, 2017). "Moreover, infection with the M448R-deficient ASFV mutant leads to increased IRF1 protein stability and elevated expression of IRF1 target genes, including OAS1, OAS2, and ZBP1." (PMID 42262133, 2026). "Thus, the expression levels of DDX58, DHX58, IFIH1, MX1, and OAS2 decreased slightly as infection with 26544/OG10 progressed (higher fold-changes at 3 hpi compared to 21 hpi)." (PMID 40530033, 2025). "OAS2 and OAS3 recognize dsRNA in different ways, which provides an additional means of activating RNase L, potentially reducing OAS1 activity loss during infection." (PMID 36670749, 2023). "Furthermore, all identified infection-associated ISG genes (MX1, MX2, OAS1Y/Z, OAS2, ISG15, IFI6, IFI44 and RSAD2) showed lower expression values in Holstein infected cells relative to Sahiwal." (PMID 35061738, 2022). "IFIT1 and OAS2 genes were induced by P/V-CPI- infection of control cells." (PMID 31083335, 2019).